ING4 (inhibitor of growth family member 4)
Diseases named in the same sentence as ING4 in open-access papers (continued):
Sharing a sentence is not in itself a finding about the gene and the disease.
tumor (continued). "However, ING4-null mice fail to show increased spontaneous tumor formation, suggesting that ING4 deficiency by itself may not be sufficient to initiate tumorigenesis." (PMID 30643005, 2019). "In this analysis, an ING4/interleukin-24 (IL-24) bicistronic adenovirus (Ad-ING-IL-24) was constructed, since IL-24 has been proven to be a potent cytokine-tumor suppressor with broad-spectrum anticarcinogenic properties as well." (PMID 31390718, 2019). "The tumour suppressor roles of ING1 and ING2 have been well established whereas candidate tumour suppressor status remains for ING3, ING4, and ING5." (PMID 31905726, 2019). "Inhibitor of growth 4 (ING4), a member of the ING family discovered in 2003, has been shown to act as a tumor suppressor and is frequently down-regulated in various human cancers." (PMID 30643005, 2019). "The inhibitor of growth (ING), a tumor suppressor, can be divided into three categories: one is ING1 and ING2, and ING4 and ING5 are classified as type II, while ING3 is different from other members." (PMID 30386928, 2019). "Although ING4 has been reported mostly as a TSG, it is inconceivable that ING4, a protein that regulates multiple cellular processes, is only involved in tumor suppression." (PMID 30643005, 2019). "ING4, the newly identified transcription activator of TDG, is a well-defined tumor suppressor in many types of cancers." (PMID 26544625, 2015). "A total of 15 tumor-bearing nude mice were randomly divided into three groups, namely, PBS, Ad-GFP, and Ad-ING4." (PMID 24581166, 2014). "As NF-kB is a key mediator of immune response, the ING4/NF-kB axis is likely to manifest in tumor-immune modulation but has not been investigated." (PMID 38968186, 2024). "Implanted tumor model analysis showed that ING4 knockout facilitated tumor growth and increased tumor weight but not in immunodeficient nude mice, which was agreement with increased PD‐L1 protein level." (PMID 37870169, 2023). "The data obtained from these tumours are also consistent with an upregulation of anti-angiogenic ING4 mRNA levels in the human xenograft tumours in vivo, with no significant changes are detected for ANG, VEGFA, HIF1α, THBS2 and COL18A1." (PMID 35513564, 2022). "Together, these results suggest that, although ING4 is involved to some degree in the regulation of the cell cycle, its principal function is not to suppress tumour development." (PMID 33925563, 2021). "Although the role of ING4 in cell cycle control has been elucidated, it is still not entirely clear how these mechanisms contribute to ING4-mediated tumor suppression in vivo." (PMID 30643005, 2019). "The effects of Ad-ING4-IL-24 transfection was investigated by means of A549 human NSCLC cell lines in vitro, as well as in vivo in a model of athymic mice who underwent subcutaneous injection of these cell lines, resulting in tumor formation." (PMID 31390718, 2019). "The multivariate Cox regression analysis went on declaring that ING4 expression was an independent prognostic biomarker for the CRC patients after adjusting with age, gender, histological type, tumor diameter and TNM stage (HR = 0.45, 95% CI = 0.29–0.71, P = 0.001)." (PMID 27806345, 2016). "In contrast to miR-650, the relative expression level of ING4 protein in responding tumor tissues was significantly higher than that in non-responding tumor tissues (P=0.022)." (PMID 23991130, 2013). "The PD-1 positivity was lower in this ING4-low/pp65-high tumor cohort but statistical significance could not be determined due to the small cohort size." (PMID 38968186, 2024). "In addition, the expression level of inhibitor of growth family member 4 (ING4), which may inhibit tumor cell growth by suppressing nuclear factor kappa B (NF-κB) signaling, has been significantly reduced in GBM." (PMID 31531345, 2019).
tumor (continued). "Moreover, the Ing4−/− mouse model does not develop cancer under reported experimental conditions, suggesting that these proteins are not tumour suppressors, or have complex yet unidentified cellular functions." (PMID 29381681, 2018). "As intended, >95% of GFP expression was found in the A549 tumor cells that had been transfected with Ad-GFP or Ad-ING4-GFP, whilst GFP was not expressed in cells transfected with Ad-DGFP or Ad-ING4-DGFP." (PMID 31390718, 2019).
cancer (26 papers, 2009 to 2025). A tumor composed of atypical neoplastic, often pleomorphic cells that invade other tissues. "ING4 is ubiquitous in multiple human tissues and is frequently mutated in various cancer cell lines." (PMID 30643005, 2019). "MYST2 has been linked to cancer by way of its role in replication and also through is interaction with the androgen receptor and tumour suppressors ING4 and ING51." (PMID 28811661, 2017). "Moreover, competition assay between ING4_v1 (full-length ING4) and ING4_v4, using cancer cells transfected with different (ING4 variant-coding) plasmid ratios, showed functional counteraction between splice variants." (PMID 34685579, 2021). "Low expression of ING4 in the cancer cells is accompanied cycle cell arrest at the G2/M phase demonstrating its role in regulation of cell cycle." (PMID 36056353, 2022). "Recently, three more miRNAs (miR-761, miR-330, and miR-423-5p) have been described to function as oncogenes in several cancers by suppressing ING4, suggesting their exploitation in the development of promising new therapeutic targets." (PMID 30643005, 2019). "This review summarizes the current literature on ING4, and efforts in the advancement of potential clinical gene therapy strategies for cancers." (PMID 30643005, 2019). "ING4 gene therapy remains a potentially viable, yet underdeveloped, treatment for cancers, and extensive preclinical and clinical trials need to be performed." (PMID 30643005, 2019). "Extensive studies have established the potent role of Ad-ING4-IL-24, at times combined with radiotherapy, in growth inhibition, invasion suppression, apoptosis induction, and inhibition of angiogenesis in cancer therapies." (PMID 30643005, 2019). "This is consistent with previous studies that have shown that ING4 promotes cell cycle arrest in other cancer cells." (PMID 29137298, 2017). "It is likely that exogenous ING4 can control cellular pathways interfering with CRAd Δ24 life cycle following cancer cell infection." (PMID 27349517, 2016). "Fisher's exact test was used to examine the correlation of ING4 expression in cancer with clinicopathological characteristics." (PMID 27806345, 2016). "Accordant with the results of western blot, 9 of 10 (90%) cancer tissues had higher delta Ct values of ING4 amplification compared with normal tissues, which meant that ING4 expression was down-regulated in cancers." (PMID 27806345, 2016). "The results of IHC indicated that ING4 was mainly located in the nucleus, and ING4 IRS was significantly lower in 363 out of 417 (87%) cancers than the normal tissues (P < 0.001)." (PMID 27806345, 2016). "The results of western blot showed that ING4 expression was dramatically reduced in 9 of 10 (90%) cancers when compared with the normal tissues." (PMID 27806345, 2016). "Seminal observations have attributed ING4 a beneficial role in regulating cancer invasion, migration and metastasis and highlighted it as a novel therapeutic target." (PMID 19250543, 2009). "Our data are in accordance with findings in cancer cell lines and patients who exhibited dramatically decreased ING4 levels which correlated with poorer survival and low treatment responsiveness." (PMID 19250543, 2009). "Studies have shown that ING4 inhibits NF-kB in various cancer types." (PMID 38968186, 2024). "Accordingly, loss of ING4 expression and pathogenic mutations have been reported in various types of human cancer cells, which support its role as a TSG regulating cell growth playing role in avoiding cancer development." (PMID 36056353, 2022). "Furthermore, ING4 is known to regulate several other processes like apoptosis, autophagy, angiogenesis, DNA repair, and malignant phenotype of cancer cells." (PMID 36056353, 2022).
cancer (continued). "However, ING4 controls the secretion of chemokines, resulting in the promotion of cancer cell proliferation." (PMID 35804879, 2022). "Combined, these results suggest that ING4 is a significant regulator of the signalling pathways in the tumorigenic progress of miR-650 and provides promising biomarker and therapeutic target for human cancer." (PMID 35331235, 2022). "Interestingly, accumulating studies have suggested that ING4 is a downstream target of miR-650 in many types of cancer, such as HCC, LC, CRC, GC, and BC." (PMID 35331235, 2022). "In addition, ING4 splice variants with a lack of NLS weakened inhibitory effect on cell growth probably due to their reduced activation of the p21 promoter when compared to ING4 with the intact NLS in three cancer cell lines." (PMID 34685579, 2021). "Moreover, the ING4-IL-24 double gene can inhibit the proliferation of cancer cells intracellularly and extracellularly." (PMID 34685354, 2021). "In addition, ING4 can also trigger apoptosis in several other cancer cell lines, such as HepG2, A549, PANC-1, SW579, and SPC-A1." (PMID 30643005, 2019). "Decreased expression or dysregulation of ING4 is widely seen in diverse types of cancers." (PMID 30643005, 2019). "ING4 also increases cancer cell sensitivity to chemotherapeutic drugs." (PMID 29137298, 2017). "Therefore, the published data and our own observations strongly suggest that vector-mediated ING4 expression can suppress cancer cell proliferative status thereby, creating an environment unfavorable for CRAd propagation." (PMID 27349517, 2016). "It is notable that our initial hypothesis was based on regulation of NF-kB by ING4 in cancer." (PMID 38968186, 2024). "Since PD‐L1 on cancer cells binding to PD‐1 on T cells results in inhibition of T cell activity and proliferation, immunohistochemical analysis showed that high expression of ING4 was correlation a low level of PD‐L1 and a high level of CD8+ T cells in LUSC tissues." (PMID 37870169, 2023). "Thus, we speculate that reversing Ras-mediated ING4 inhibition to activate Fas expression is a potential therapeutic approach for Ras-driven cancers." (PMID 26544625, 2015). "Our results showing decreased CD4 CTLs in Ing4-deleted tumors correlating with metastasis and poor patient survival are consistent with the roles of CD4 CTLs in anti-cancer immunity." (PMID 38968186, 2024). "Extensive genes have been identified as the target of miR-761 in numerous cancers, including HDAC1, Rab3D, Runx3, Mitofusin-2, CXCR1, TRIM29, MSI1, ING4, TIMP2, and GSK3β." (PMID 32185226, 2020). "Compelling evidence suggests that the human ING4 protein is highly expressed in normal tissues, but that its expression is dramatically decreased in some types of cancer, suggesting that its aberrant expression may contribute to the pathogenesis of these cancers." (PMID 30643005, 2019). "Cancer treatment is often limited due to the development of diverse multidrug resistance (MDR); however, ING4 overexpression enhances the sensitivity to cancer chemotherapies." (PMID 30643005, 2019).
cancer (continued). "In agreement with ING4 and ING5 being required for normal cell cycle progression, we observed that ING3 is also required for cellular proliferation of cancer cells." (PMID 29381681, 2018). "Inhibitor of growth 4 (ING4) is a member of the ING family, but its impact on cancer stem cells in RCC is still unknown." (PMID 35496267, 2022). "Beyond the cell cycle regulator CDKN1B (12p13.1), further potentially relevant cancer genes on 12p may for example include CD9, ING4, and BCL-G." (PMID 26293672, 2015). "Therefore, reversing Ras-mediated ING4 suppression to activate TDG expression and subsequent Fas expression could a promising approach for the target therapy of pancreatic cancer and other Ras-driven cancers." (PMID 26544625, 2015). "Both ING4 and OSM exert a negative effect on cancer cells rather than normal cells." (PMID 35075768, 2022).
infection (2 papers, 2016 to 2017). The state of being infected such as from the introduction of a foreign agent such as serum, vaccine, antigenic substance or organism. "Infection of SKOV3ip.1 cells revealed that cytotoxic CRAd-ING4 effects were markedly improved as compared to control CRAd." (PMID 27349517, 2016). "To evaluate oncolytic potency of armed CRAd-IL24 and CRAd-ING4 with respect to control CRAd we carried out multiple assays measuring cell viability following infection at a wide range of MOIs." (PMID 27349517, 2016). "While CRAd-IL24 and CRAd-ING4 infection resulted in somewhat similar cytotoxicity increase in SKO3luc cells as compared to control CRAd we did not observe any significant differences between CRAd vectors in OV-4 and IOSE-120/523 cells." (PMID 27349517, 2016). "The lack of correlation between viral genome amplification and infectious progeny titers observed following CRAd-ING4 infection suggested that ING4 expression may interfere with infectious viral particles assembly within nucleus of infected cells." (PMID 27349517, 2016). "Finally, we tested if supplementing infection media with Avastin (Bevacizumab), a recombinant humanised monoclonal antibody developed against soluble VEGF to prevent receptor binding, may increase oncolytic potency of CRAd-IL24 and/or CRAd-ING4 in OvCa cells." (PMID 27349517, 2016).
neoplastic disorders (1 paper, 2019). "In addition, emerging evidence has indicated that abnormalities in ING4 expression and function play key roles in non-neoplastic disorders." (PMID 30643005, 2019).
ING4 also shares sentences with these, for which no sentence is quoted: leukemia (3 papers); head and neck squamous cell carcinoma (2); osteosarcoma (2); astrocytomas (1); brain cancer (1); carcinoid tumor (1); clear cell renal carcinoma (1); colorectal adenocarcinoma (1); complex regional pain syndrome (1); dysplastic nevi (1); fibrosis (1); gastric adenocarcinoma (1); head and neck carcinoma (1); Intellectual disability (1); invasive ductal carcinoma (1); lobular carcinoma (1); lung squamous cell carcinoma (1); lymphoma (1); metastasis (1); metastatic tumor (1); myotonic dystrophy (1); nasopharyngeal carcinoma (1); neuroblastoma (1); non-small cell lung carcinoma (1); oral candidiasis (1); pancreatic adenocarcinoma (1); prostate tumors (1); psoriatic arthritis (1); renal cell carcinoma (1); rhabdoid tumor (1).
A further 2 diseases each share a sentence with ING4 in 1 paper.